PIM2 (Pim-2 proto-oncogene, serine/threonine kinase)
Diseases named in the same sentence as PIM2 in open-access papers (continued):
Sharing a sentence is not in itself a finding about the gene and the disease.
cancer (continued). "PIM kinases, including PIM1, PIM2, and PIM3, are serine/threonine kinases frequently overexpressed in tumors and contribute to cancer cell proliferation, survival, and metastasis." (PMID 41199316, 2025). "Regarding the regulation of cancer cell necroptosis by SPOP, this study suggests that PIM2 and ERK2 kinase can fine-tune key molecules through phosphorylating T403, T412, and S413 of RIPK3." (PMID 39540935, 2024). "Others have shown that PIM1 and PIM2 mRNA expression correlated with mRNA expression of CD44 and CD133, two markers of glioblastoma cancer stem cells." (PMID 35892829, 2022). "Genes such are GSTA4, GSTO2, KLK3, PGF were down-regulated and E2F2, MMP9, PIM2, VEGFC are up-regulated in all cancer nodules." (PMID 34209090, 2021). "The PIM1, PIM2, and PIM3 serine/threonine kinases play a role in the proliferation and survival of cancer cells." (PMID 31073371, 2019). "The phosphorylation of PKM2T454 by PIM2 led to an increase in PKM2 expression and the Warburg effect in cancer cells." (PMID 26959741, 2016). "PIM protein family, short-lived serine/threonine kinases (PIM1, PIM2 and PIM3), are weak oncogenes but contribute to tumorigenesis as cancer targets." (PMID 25749522, 2015). "We identified more novel interacted proteins with PIM kinases (PIM1, PIM2 and PIM3) and further shed light on more molecular mechanisms of PIM kinases in cancer." (PMID 25749522, 2015). "The PIM2- and ERK2-mediated phosphorylation of RIPK3 at its degron motifs may be a key signaling pathway determining whether cancer cells survive or undergo necroptotic death." (PMID 39540935, 2024). "Over-expression of PIM1 and PIM2 kinases has been reported in hematologic malignancies also in solid tumors such as diffuse large B cell lymphomas (DLBCL) and prostate cancer, thus, these findings make it an attractive target for cancer therapy." (PMID 29564572, 2018). "Furthermore, in these cancer types, PIM1 and PIM2 can be overexpressed in the same tumors, which suggest that there is only a partial redundancy among them and share some common physiological properties." (PMID 27901106, 2016). "The high level of expression of PIM1 and PIM2 in ABC-DLBCL and the reported synergistic effect of these two kinases with c-MYC in several cancers, prompted us to test the efficiency of the pan-PIM kinase inhibitor AZD1208 in preventing proliferation of aggressive NHL-derived cell lines." (PMID 26643319, 2015). "Despite the widespread use of PARP1 inhibitors across various cancers, the combined effects of PARP1 inhibitors and PIM‐2 inhibitors in enhancing DNA damage have not been fully explored." (PMID 40557764, 2025). "Even though HIF-1α and HIF-2α are dominantly expressed in cancer cells, our present data could not exclude that the HIF-3α was also involved in PIM2 regulation." (PMID 24505470, 2014).
hematologic cancers (2 papers, 2018 to 2023). "The PIM family consists of three members, PIM1, PIM2, and PIM3, from which PIM1 and PIM3 have been shown to be upregulated in solid cancers, while PIM2 mostly in hematological cancers." (PMID 37943821, 2023). "Single-agent INCB053914 upregulated PIM2 and inhibited phosphorylation of multiple substrates in hematologic cancer cell lines as well as in patient-derived primary AML cells." (PMID 29927999, 2018).
hematologic diseases (2 papers, 2021 to 2023). "The family of pim kinases comprises three isozymes: pim‐1, pim‐2, and pim‐3, all of which are reported to be overexpressed in several hematologic malignancies." (PMID 37162273, 2023).
infection (2 papers, 2022 to 2026). The state of being infected such as from the introduction of a foreign agent such as serum, vaccine, antigenic substance or organism. "For example, PIM2 can also phosphorylate BAD, and we have shown that PIM2 expression is upregulated by LVS infection." (PMID 35873156, 2022). "PIM kinases (PIM1, PIM2, PIM3) are serine/threonine kinases implicated in infection and reactivation of various viruses, but their roles in HIV-1 gene expression and particle production remain unclear." (PMID 41754420, 2026).
PIM2 also shares sentences with these, for which no sentence is quoted: multiple myeloma (10 papers); diffuse large B-cell lymphoma (4); follicular lymphoma (2); gastric tumors (2); viral infection (2); airway hyperresponsiveness (1); autoimmune disease (1); brain tumors (1); CNS lymphomas (1); COVID-19 (1); Disseminated intravascular coagulation (1); endometrial tumors (1); gastritis (1); glioblastoma (1); injury (1); liposarcoma (1); MALT lymphoma (1); meningitis (1); meningoencephalitis (1); monoclonal gammopathy of undetermined significance (1); Myelodysplasia (1); nodal marginal zone lymphoma (1); Parkinson disease (1); respiratory failure (1).